C2CD5 (C2 calcium dependent domain containing 5)
Description:
Required for insulin-stimulated glucose transport and glucose transporter SLC2A4/GLUT4 translocation from intracellular glucose storage vesicle (GSV) to the plasma membrane (PM) in adipocytes. Binds phospholipid membranes in a calcium-dependent manner and is necessary for the optimal membrane fusion between SLC2A4/GLUT4 GSV and the PM.
Synonyms: CDP138; KIAA0528
Tractability: Antibody: UniProt places it where antibodies can reach, with high confidence; its Gene Ontology location is reachable by antibodies, with high confidence. PROTAC: ubiquitination databases record sites on it; its protein half-life has been measured.
Gene: Protein-coding gene on chromosome 12 (22,448,567 to 22,544,574, reverse strand). Ensembl gene ENSG00000111731.
Subcellular location: Cytoplasmic vesicle membrane; Cytoplasm, cell cortex; Cell membrane; Cell projection, ruffle
Subcellular location (Human Protein Atlas): Cytosol; Centriolar satellite
Pathways (Reactome):
Vesicle-mediated transport: Translocation of SLC2A4 (GLUT4) to the plasma membrane
Gene Ontology:
Molecular function: calcium ion binding; calcium-dependent phospholipid binding
Biological process: insulin receptor signaling pathway; intracellular protein transmembrane transport; positive regulation of protein targeting to membrane; positive regulation of vesicle fusion; positive regulation of D-glucose transmembrane transport; protein localization to plasma membrane; intracellular protein localization
Cellular component: cell cortex; cytoplasmic vesicle membrane; cytosol; plasma membrane; ruffle membrane; ruffle
Genetic constraint (gnomAD): Loss-of-function variants: 17 observed, 33.78 expected, observed/expected ratio (o/e) 0.5, 90% interval 0.34 to 0.75. The upper end of that interval is the gene's LOEUF score, 0.75, which puts it in group 3 of 6, group 1 being the genes least tolerant of losing a copy. Missense variants: 298 observed, 447.06 expected, observed/expected ratio (o/e) 0.67, 90% interval 0.61 to 0.73. Synonymous variants: 154 observed, 158.91 expected, observed/expected ratio (o/e) 0.97, 90% interval 0.85 to 1.11.
Homologues: Orthologues: chimpanzee C2CD5 (99% identical), dog C2CD5 (99% identical), rabbit C2CD5 (98% identical), rat C2cd5 (96% identical), macaque C2CD5 (95% identical), pig C2CD5 (93% identical), guinea pig C2CD5 (92% identical), mouse C2cd5 (92% identical), zebrafish c2cd5 (81% identical), tropical clawed frog c2cd5 (73% identical).
Diseases named in the same sentence as C2CD5 in open-access papers:
C2CD5 is named in the same sentence as 7 diseases in open-access papers, as found by Europe PMC text mining. Sharing a sentence is not in itself a finding about the gene and the disease. The quoted sentences say what the papers report.
breast carcinoma (4 papers, 2015 to 2019). "Fibroblast growth factor (acidic) intracellular binding protein (FIBP) and KIAA0528 (C2 calcium-dependent domain containing 5) have recently been identified as CDK5 binding partners in non-neuronal cells, and are required for growth and migration of breast cancer cells." (PMID 31534152, 2019).
cancer (3 papers, 2017 to 2021). A tumor composed of atypical neoplastic, often pleomorphic cells that invade other tissues. "Analyzing protein–protein interaction network in STRING database, SLC2A4 also participates in the translocation of SLC2A4 (GLUT4) to the plasma membrane and protein localization to plasma membrane through enriched proteins such as EXOC5 and C2CD5, which play an important role in human cancers." (PMID 34488531, 2021).
infection (1 paper, 2023). The state of being infected such as from the introduction of a foreign agent such as serum, vaccine, antigenic substance or organism. "The FAM168B, RAF1, HESX1, USP8, C2CD5, PIGC, ENSGALG00000053041, and ENSGALT00000092369 were found to be top driver genes shared among dpi, body weight post-infection, and propionate and valerate cecal contents." (PMID 36902251, 2023).
C2CD5 also shares sentences with these, for which no sentence is quoted: lung carcinoma (2 papers); diabetes (1); lung adenocarcinoma (1); lymph node metastasis (1).